SQSTM1 (sequestosome 1)
Diseases named in the same sentence as SQSTM1 in open-access papers (continued):
Sharing a sentence is not in itself a finding about the gene and the disease.
amyotrophic lateral sclerosis (41 papers, 2014 to 2025). Amyotrophic lateral sclerosis (ALS) is a neurodegenerative disease characterized by progressive muscular paralysis reflecting degeneration of motor neurons in the primary motor cortex, corticospinal tracts, brainstem and spinal cord. "Pathogenic variants in SQSTM1 have been most commonly linked to Paget's disease of bone, amyotrophic lateral sclerosis (ALS), and frontotemporal dementia (FTD)." (PMID 40772172, 2025). "Among them, SQSTM1 p.His359del is recorded in the ClinVar database, classified as a variant of uncertain significance for frontotemporal dementia and/or amyotrophic lateral sclerosis 1 (FTD-ALS1) and Paget disease of bone 2, early-onset (PDB2)." (PMID 40170896, 2025). "The SQSTM1 p.Pro392Leu variant has already been detected in diverse cohorts of patients displaying frontotemporal dementia with amyotrophic lateral sclerosis from different populations." (PMID 40208338, 2025). "Nucleotide changes on SQSTM1 are known to contribute to the origin of neurological alterations, implicated in the pathogenesis of amyotrophic lateral sclerosis and frontotemporal dementia." (PMID 38002079, 2023). "SQSTM1 mutations are associated with a spectrum of multisystem proteinopathy, including Paget disease of the bone, amyotrophic lateral sclerosis, frontotemporal dementia, and distal myopathy with rimmed vacuoles (MRV)." (PMID 36998782, 2023). "Mutations in SQSTM1 contribute to neurodegeneration in amyotrophic lateral sclerosis and frontotemporal dementia." (PMID 37304079, 2023). "A study has shown that mutations in SQSTM1, which codes for p62, are a causative factor in Paget disease of bone, as well as amyotrophic lateral sclerosis and frontotemporal dementia." (PMID 35898936, 2022). "Mutations in the p62/SQSTM1 gene have been known to be associated with patients with amyotrophic lateral sclerosis (ALS), frontotemporal dementia (FTD), and Parkinson disease (PD)." (PMID 33557921, 2021). "Missense mutations in SQSTM1 have been primarily associated with amyotrophic lateral sclerosis (ALS), frontotemporal lobar degeneration (FTD), and Paget’s disease of bone (PDB)." (PMID 34774801, 2021). "Dominant mutations in SQSTM1 have been also related with Paget’s disease of the bone, amyotrophic lateral sclerosis and frontotemporal dementia (ALS/FTD)." (PMID 33917666, 2021). "Missense mutations of SQSTM1 cause ALS (amyotrophic lateral sclerosis), PDB (Paget’s disease of bone) or FTLD (frontotemporal lobar degeneration)." (PMID 34206503, 2021). "Heterozygous SQSTM1 variants have been associated with amyotrophic lateral sclerosis, Paget's disease, frontotemporal dementia, and distal hereditary myopathy with rimmed vacuoles." (PMID 33135846, 2020). "Mutations in SQSTM1 have also been reported in other diseases, like amyotrophic lateral sclerosis, in cohorts with familiar, sporadic and frontotemporal dementia—ALS, from Europe, the USA and Japan." (PMID 28255281, 2017). "Loss of Sequestosome-1 is hypothesized to enhance neurodegeneration progression in several diseases, including amyotrophic lateral sclerosis (ALS) and frontotemporal disorders (FTD)." (PMID 39006307, 2023). "Identical variants in SQSTM1 are associated with four different phenotypes: amyotrophic lateral sclerosis (ALS), frontotemporal dementia, Paget’s disease of the bone, and distal myopathy." (PMID 37628614, 2023). "SQSTM1 has been primarily associated with amyotrophic lateral sclerosis (ALS), frontotemporal lobar degeneration (FTD), and Paget disease of bone." (PMID 40396030, 2022). "However, further studies on p62/SQSTM1 are very important with respect to human health since deficiency or loss of p62/SQSTM1 could lead to amyotrophic lateral sclerosis, frontotemporal dementia and childhood- or adolescence-onset neurodegenerative disorders." (PMID 35011599, 2021).
amyotrophic lateral sclerosis (continued). "Mutations in the SQSTM1 gene have been associated with several diseases including amyotrophic lateral sclerosis (ALS), frontotemporal dementia (FD), and neurodegeneration with ataxia." (PMID 29343546, 2018). "Mutations in the gene coding for Sequestosome 1 (SQSTM1) have been genetically associated with amyotrophic lateral sclerosis (ALS) and Paget disease of bone." (PMID 24899140, 2014). "Amyotrophic lateral sclerosis (ALS) is characterised by the presence of genetic mutations in autophagy-related genes, including SQSTM1, OPTN, TBK1, VCP, and C9ORF72, which have been found to be linked to family variants of the illness." (PMID 37760929, 2023). "Some SQSTM1 gene mutations linked to PDB were reported in chronic nervous system disorders, such as frontotemporal dementia and amyotrophic lateral sclerosis, suggesting that both PDB and nervous system diseases may coexist." (PMID 41306824, 2025). "Furthermore, the network also included Sqstm1, which is connected to frontotemporal dementia and amyotrophic lateral sclerosis." (PMID 36089582, 2022). "SQSTM1, which has been identified in FTD in 2012, suggesting a role in the pathogenesis of neurodegenerative disease, is initially considered as a monogenic cause of Paget disease of bone (PDB) in 2002 and amyotrophic lateral sclerosis in 2011." (PMID 29467647, 2018). "SQSTM1 variations are associated with multisystem proteinopathies (MSPs), including Paget disease of the bone (PDB), amyotrophic lateral sclerosis (ALS), frontotemporal dementia (FTD), and myopathy with rimmed vacuoles (MRV)." (PMID 36998782, 2023). "We identified a nonsense variant in SQSTM1 (p.Y140X), a gene associated with FTD and amyotrophic lateral sclerosis (ALS)." (PMID 35650585, 2022). "Recently, heterozygous SQSTM1 mutations have also been found in other diseases like Paget's disease (PDB), amyotrophic lateral sclerosis (ALS), and frontotemporal dementia (FTLD)." (PMID 33135846, 2020). "SQSTM1 is a gene involved in autophagy and suspected to play a role in neurodegenerative diseases, including amyotrophic lateral sclerosis (ALS)." (PMID 31727120, 2019). "For example, various mutations of Sqstm1 have been identified in patients with Paget disease of bone (PDB), amyotrophic lateral sclerosis (ALS) and frontotemporal lobar degeneration (FTLD)." (PMID 26483381, 2015). "Three of these variants have been described in patients with AD, PD or frontotemporal lobar degeneration and amyotrophic lateral sclerosis (Patient A:PSEN2 p.D439A;16, 17 B:CHMP2B p.I29V;18 and C:SQSTM1 p.A33V,19, 20)." (PMID 26836416, 2016).
frontotemporal dementia (40 papers, 2014 to 2025). Frontotemporal dementia (FTD) comprises a group of neurodegenerative disorders, characterized by progressive changes in behavior, executive dysfunction and language impairment, as a result of degeneration of the medial prefrontal and frontoinsular cortices. "Nonsense mutations in SQSTM1 were also associated with frontotemporal dementia and progressive ataxia movement disorders in previous studies." (PMID 36998782, 2023). "In the present study, we analyzed the SQSTM1 coding sequence for mutations in an extended cohort of 1,808 patients with frontotemporal lobar degeneration (FTLD), ascertained within the European Early-Onset Dementia consortium." (PMID 24899140, 2014). "SQSTM1 variants are associated to frontotemporal dementia and/or amyotrophic lateral sclerosis-3 (FTDALS3, MIM #616437) while RORA alterations are associated to intellectual developmental disorder with or without epilepsy or cerebellar ataxia (IDDECA, MIM #618060)." (PMID 40208338, 2025). "Likewise, SQSTM1 mutations have been also detected in a limited number of patients with only frontotemporal dementia or ALS." (PMID 36035996, 2022). "Other examples of less-common risk alleles are those of SQSTM1 associated with frontotemporal dementia (c.1142C>T, K341V and K344E) or muscle disorders such as sporadic inclusion body myositis (G194R) and distal myopathies with rimmed vacuoles (p.G351_P388del and p.Glu389delinsAspLysTer)." (PMID 33147747, 2020). "Mutations in SQSTM1/p62 are found in frontotemporal dementia (FTD) and amyotrophic lateral sclerosis in adults (ALS)." (PMID 32087199, 2020). "The Sqstm1 gene encodes p62, and mutations in the Sqstm1 gene have previously been reported in both ALS and the related disorder frontotemporal dementia." (PMID 36089582, 2022). "Thus, MATR3 is among the family of genes including VCP, HNRNPA1, HNRNPA2B1 and SQSTM1 that cause “multisystem proteinopathy” associated with either one or a combination of ALS/frontotemporal dementia (FTD), VCPDM and Paget’s disease of bone." (PMID 32811564, 2020). "Intriguingly, a significant number of genes involved in the pathogenesis of PDB (namely SQSTM1, VCP, PFN1, and OPTN) have been also associated with neurodegenerative disorders (e.g., ALS or frontotemporal dementia) suggesting shared pathophysiological mechanisms." (PMID 36035996, 2022). "For example, several genes causing ALS and/or frontotemporal dementia (C9orf72, VCP, SQSTM1, OPTN, UBQLN2, GRN, CHMP2B) affect the autophagic machinery; and some Alzheimer’s Disease genes (APOE, TREM2, CD33, ABCA7) are preferentially or exclusively expressed in microglia." (PMID 33892821, 2021). "Several mutations in p62/SQSTM1 have been identified in cases of familial and sporadic amyotrophic lateral sclerosis (ALS) and frontotemporal lobar degeneration (FTLD), leading to loss of function of p62/SQSTM1 in selective autophagy, or a decreased interaction with Keap143." (PMID 32377374, 2020). "Disruption of cargo recognition for sequestration can also occur due to mutations in the p62-encoding SQSTM1 gene, which are associated with sporadic ALS, frontotemporal dementia (FTD), and Paget’s disease of bone marrow and disorders featuring p62-positive intra-neural inclusion." (PMID 31527516, 2019). "TANK-binding kinase 1 (TBK1) phosphorylates SQSTM1 and OPTN, and haploinsufficiency of TBK1 is associated with both ALS and frontotemporal dementia (FTD)." (PMID 37307819, 2024). "Mutations of SQSTM1 have been associated with the risk for frontotemporal dementia (FTD), with mutations leading to disrupted interactions between KEAP1 and SQSTM1." (PMID 35052512, 2021). "Recently, mutations in the SQSTM1 gene have been identified in patients with ALS and ALS/frontotemporal dementia (FTD)." (PMID 29843805, 2018).
frontotemporal dementia (continued). "Up to 15% of ALS patients also develop signs of frontotemporal dementia (FTD) and several genes, including C9ORF72, TDP-43, VCP, SQSTM1, OPTN, UBQLN2 and TBK1, contribute to the etiology of both ALS and FTD." (PMID 37220877, 2023). "SQSTM1/p62 is a standard component of neuronal and glial cytoplasmic inclusions that characterize many neurological disorders, including ALS and frontotemporal dementia (FTD)." (PMID 39316747, 2024). "Two patients had SQSTM1 variants; these have been described in familial and apparently sporadic MND, as well as in frontotemporal dementia (FTD) without MND, and are also associated with multisystem disease." (PMID 36515702, 2023). "Given the patient’s family history of frontotemporal dementia (FTD) in a maternal uncle, the genetic analysis was extended to include the most common genes associated with FTD (TARDBP, GRN, TBK1, CHMP2B, SQSTM1, UBQLN2, VCP and MAPT) but no additional variants of clinical significance were detected." (PMID 40659544, 2025).
hepatocellular carcinoma (33 papers, 2015 to 2025). A malignant tumor that arises from hepatocytes. "In this sense, it has been shown that NF-κB in hepatoma-associated M2-like macrophages forms aggresome-like structures (ALS) which are recognized by the p62/SQSTM1 complex and in which NF-κB is degraded." (PMID 35620053, 2022). "Obesity-stimulated liver steatosis represents a growing cause of hepatocellular carcinoma, and is associated with inhibition of autophagy and the accumulation of p62/SQSTM1." (PMID 33276631, 2020). "Such five genes are HDAC1, RHEB, ATIC, SPNS1, and SQSTM1, that were associated with overall survival in hepatocellular carcinoma patients." (PMID 33194736, 2020). "The upregulated p62/SQSTM1-induced Nrf2 activation through Keap1 degradation by autophagy deficiency was analogously detected in the liver tissues of human hepatocellular carcinoma." (PMID 30642133, 2019). "Similarly, CEP treatment caused accumulation of LC3B-II and SQSTM1 in SMMC-7721 (a human hepatocellular carcinoma cell line), K562 (a human leukemia cell line), and A549 (a human lung cancer cell line) cells." (PMID 31699152, 2019). "Through Nrf2-dependent metabolic reprogramming, p62/SQSTM1 increases the malignancy of HCV-positive hepatocellular carcinoma." (PMID 35326612, 2022). "This is consistent with previous reports showing that trehalose upregulates Sqstm1 levels in mouse hepatoma cells or motor neuron cells." (PMID 33277792, 2021). "The conditional medium from hepatoma cell line ML-14a elevated M2-like expression pattern in BMDMs by stimulating sequestosome 1 (p62/SQSTM1) depended ubiquitination of NF-κB p65 followed by autophagy-mediated degradation of NF-κB p65." (PMID 33990205, 2021). "Overexpressing NBR1 promotes SQSTM1 accumulation and phosphorylation in liquid-like bodies and SQSTM1-mediated activation of NFE2L2/NRF2 provides hepatocellular carcinoma cells proliferation potency." (PMID 34829881, 2021). "Moreover, aberrant accumulation of Sqstm1-positive aggregated structures has been detected in patients with liver disorders including non-alcoholic steatohepatitis and α1-antitrypsin deficiency, tumors such as hepatocellular carcinoma and various neurodegenerative diseases." (PMID 26483381, 2015). "The accumulation of autophagy cargo receptor p62 (also known as SQSTM1) is a notable feature observed in many cancers, and it is correlated with poor clinical outcomes among hepatocellular carcinoma patients and increased metastasis occurrence in nasopharyngeal carcinoma." (PMID 39273093, 2024). "Furthermore, overexpression of p62/SQSTM1 in hepatocytes is able to mediate oncogenesis, as p62/SQSTM1 is a major component of Mallory bodies, which accumulate in the human hepatocellular carcinoma." (PMID 33802014, 2021). "We found that deptropine increased LC3B-II expression and the number of autophagosomes, but failed to degrade SQSTM1/p62 by blocking the fusion of autophagosomes and lysosomes, and finally caused the death of hepatoma cells." (PMID 32570749, 2020). "In addition, NF-κB RELA cytosolic ubiquitination is stimulated by TLR2 signaling and leads to its degradation through SQSTM1/p62-mediated autophagy, while inhibition of autophagy rescues NF-κB activity and shapes hepatoma-polarized M2 macrophages." (PMID 31915514, 2019). "Since SQSTM1 is upregulated in hepatoma cells 6 days after the beginning of HCV replication, we conclude that SQSTM1 may be one of the key regulators that induce metabolic reprogramming in HCV infected cells towards the development of hepatocellular carcinoma." (PMID 31717433, 2019). "Considerable cytochemical and ultrastructural similarities with HeLa-cell sequestosomes are shown by the hyaline bodies reported by Denk and coworkers in hepatocellular carcinoma, characterized by a thinly fibrillar ultrastructure and heavy reactivity for p62/SQSTM1 protein and for Congo Red." (PMID 30223470, 2018).
hepatocellular carcinoma (continued). "Accumulation of SQSTM1 reflects impaired autophagy, which is related to the carcinogenesis and progression of various tumors, including hepatocellular carcinoma (HCC)." (PMID 39015499, 2024). "Moreover, SQSTM1 accumulation by autophagy inactivation contributes to the development of benign hepatomas in mouse models, but the underlying mechanism is not known." (PMID 34829743, 2021). "In hepatocellular carcinoma, hexokinase 2 (HK2), a rate-limiting enzyme in glycolysis, is recognized by the autophagy receptor SQSTM1 and subsequently subjected to selective degradation via the autophagy process." (PMID 38291438, 2024). "Increased accumulation of p62/SQSTM1, hampering the KEAP1–NRF2 interaction, is a common characteristic in hepatocellular carcinoma." (PMID 35326187, 2022). "In these settings, in response to hepatoma‐derived factors, macrophages use the toll‐like receptor 2 (TLR2) pathway to get the NF‐κB/RELA cytosolic ubiquitination, which is then degraded through a SQSTM1/p62‐dependent mechanism, thus favoring an M2‐like polarization." (PMID 39439196, 2025). "In human and murine models of hepatocellular carcinomas (HCC), induction of autophagy led to CCND1 ubiquitination and its recruitment into autophagosomes via SQSTM1, formation of autophago-lysosomes, and degradation with suppression of tumor growth." (PMID 34445095, 2021). "In hepatocellular carcinoma, the lncRNAs phosphatase and tensin homolog pseudogene 1 (PTENP1) activate autophagy, interacting with miR-17, miR-19b, and miR-20a, denying their targeting of the autophagy genes ULK1, ATG7 and p62/SQSTM1, and the tumor suppressor PTEN." (PMID 33194736, 2020). "To understand why the SQSTM1/p62 protein accumulated in HepG2 cells and was not degraded in Hep3B cells, we investigated whether deptropine could block autophagic flux in hepatoma cells by transfecting cells with the mCherry-green fluorescent protein (GFP)-LC3 tandem reporter plasmid." (PMID 32570749, 2020). "Indeed, in the hepatocellular carcinoma cell line HepG2, MEN1-KD did not inhibit the transcription of lysosomal and autophagic genes such as CTSB and SQSTM1." (PMID 40057469, 2025).